TSC2 (TSC complex subunit 2)
Diseases named in the same sentence as TSC2 in open-access papers (continued):
Sharing a sentence is not in itself a finding about the gene and the disease.
epilepsy (continued). "Indeed, several causal mutations have been identified in patients with epilepsy, the most prominent of these being mutations in PTEN and tuberous sclerosis complexes 1 and 2 (TSC1, TSC2)." (PMID 24672426, 2014). "In addition, individuals with mutations in TSC1, TSC2, and PTEN, all of which influence cAMP activity and the MTOR pathway all display neurological findings and an increased prevalence of epilepsy." (PMID 24260271, 2013). "Indeed, the same aberrations in cortical cytoarchitecture, hippocampal disturbances and spontaneous epilepsy that have been detected in RGC-targeted Tsc2 mutants were observed in RGC-targeted Tsc1 mutant mice." (PMID 23744272, 2013). "Thus, most Tsc1+/− and Tsc2+/− mice are not suitable as models of TSC-associated epilepsy, or brain symptoms caused by a combination of the first hit (normal-sized neurons and glial cells) and the second hit (abnormal giant cells)." (PMID 34206526, 2021). "TSC is a neurodevelopmental disorder characterized by autism, epilepsy, and intellectual disability, and to study the role of TSC2 in synaptic plasticity, we generated mice lacking one copy of the Tsc2 gene, which will henceforth be referred to as the Tsc2+/− mouse." (PMID 33054857, 2020). "Besides factors related to epilepsy and epilepsy treatment, several other factors have also been correlated with cognitive functioning, including if the patient had a mutation in TSC1 or TSC2." (PMID 27878438, 2017). "This in‐frame deletion co‐occurs with a definite TSC‐causing variant in TSC2 exon 5 (TSC2 c.569dup, p.Y190*) in an infant who fulfils the diagnostic criteria for TSC (cortical tubers, SEGA, subependymal nodules, hypomelanotic macules, renal angiomyolipoma, epilepsy)." (PMID 26703369, 2016). "Conversely, genetic inactivation of Tsc1 and Tsc2 in early embryonic neural progenitors such as NEPs and RGCs, respectively, resulted in very similar neocortical and hippocampal alterations, lamination defects, generation of enlarged cells, cell heterotopias, and epilepsy." (PMID 23744272, 2013). "Beyond TSC2 and SCN1A patients, who, as expected, demonstrated high seizure reduction rates, other monogenic epilepsies also showed favorable responses." (PMID 40126049, 2025). "Subependymal nodules (SEN) and cortical tubers were the most frequently appearing lesions, followed by hypomelanotic macules (HM) and epilepsy in TSC1 and TSC2 patients." (PMID 36232477, 2022). "Statistical analysis revealed that epilepsy occurs with equal prevalence between TSC1 and TSC2 groups (Z = −0.53, df = 1, p = 0.60)." (PMID 35440050, 2022). "The tuber load, usually higher in individuals with TSC2, might have a role in creating more complex and diffuse abnormal networks, with fewer regions showing normal brain cortex, leading more frequently to drug resistant epilepsy and higher rates of co-morbidities." (PMID 34566842, 2021). "During the follow-up period, a total of 148/174 (85.06%) patients suffered from epilepsy (TSC1:TSC2: NMI = 24:109:15), with 65.54% of those patients manifesting epilepsy within the first year of life." (PMID 32211034, 2020). "A patient with TSC due to a previously unreported deletion of exons 4-8 in TSC2, ASM-resistant epilepsy who responded favorably to phenytoin (PHT) and in whom everolimus led to regression of multifocal epilepsy, to the best of our knowledge, has not been previously reported." (PMID 40161113, 2025). "Patients with TSC2 variations may benefit from mTOR inhibitors like everolimus, which have demonstrated a >50% reduction in seizure frequency in TSC-related epilepsy patients." (PMID 39906551, 2024). "In our cohort, a single patient had TSC2/PKD1-CGS and, at 7 months, had epilepsy." (PMID 38671609, 2024).
epilepsy (continued). "Amongst the most well-known examples of non-ion channel-associated epilepsy genes are TSC1 and TSC2, components of the mammalian target of rapamycin (mTOR) pathway." (PMID 37834053, 2023). "The prevalence of epilepsy was slightly higher in TSC2 patients, but this was not statistically significant." (PMID 36232477, 2022). "Eighty-one epilepsy-related genes were detected; the gene most frequently detected was KCNQ2 (nine times), followed by PRRT2 (seven times), SCN1A (six times), SCN2A (five times), SPTAN1 (four times), and TSC2 (four times)." (PMID 35571021, 2022). "Everolimus, an mTOR inhibitor, has shown the ability to reverse social behavior deficits in TSC2 mice without an additional epilepsy model." (PMID 35422816, 2022). "It is therefore of potential importance that reversal of cognitive and social behavior deficits by mTORi was mostly observed in studies conducted in Tsc1+/- and Tsc2+/- mice without an additional epilepsy model." (PMID 33863288, 2021). "Genetic factors, i.e. pathogenic variants in TSC2 rather than TSC1, have been recognized as a significant risk factor for earlier and more severe epilepsy, as well as for a higher rate of cognitive impairment, with due exceptions." (PMID 32216820, 2020). "Originally, heterozygous Tsc1 or Tsc2 knockout (Tsc1± or Tsc2±) mice showed no seizure episodes, and only one report showed that approximately half of Tsc1± mice showed spontaneously transient characteristics of epilepsy." (PMID 36606143, 2022). "However, only IS and epilepsy are strongly associated with TSC2 mutations, whereas MR and neurocognitive impairment are linked to different types and location of TSC1 and TSC2 germline mutations, rather than to the specific gene in which the mutation occurred." (PMID 23744272, 2013). "TSC2 patients showed a more severe phenotype from high DD/ID frequency, tough AF and renal AML lesions, and non-remission of epilepsy." (PMID 36232477, 2022).
angiomyolipoma (64 papers, 2007 to 2025). A neoplasm with perivascular epithelioid cell differentiation often associated with tuberous sclerosis. "Patients with tuberous sclerosis complex (TSC) develop renal cysts and/or angiomyolipomas (AMLs) due to inactive mutations of either TSC1 or TSC2 and consequential mTOR hyperactivation." (PMID 39333852, 2024). "Being female (HR = 0.505, 95% CI 0.272–0.937) and underweight (HR = 0.092, 95% CI 0.011–0.800) both lowers the risk of having angiomyolipomas, but TSC2 mutations (HR = 2.568, 95% CI 1.101–5.989) and being obese (HR = 2.555, 95%CI 1.243–5.255) increases risks." (PMID 38483608, 2024). "Two of the three tested sets had verifiable TSC2 mutations–the murine TTJ and human angiomyolipoma 621 cells–which allowed us to compare a TSC2-inactive (TSC2-) to a TSC2-active (Tsc2+) state." (PMID 39456169, 2024). "Patients with TSC2 mutations had significantly earlier angiomyolipoma detection (13 vs. 23 years) and showed significantly higher rates of multiple and bilateral angiomyolipomas than those with TSC1 mutations." (PMID 38483608, 2024). "The function loss of the TSC2 gene leads to aberrant mTOR pathway activation and multiple tumors including subependymal giant cell astrocytomas, angiomyolipomas, lymphangioleiomyomatosis, and angiofibromas." (PMID 37152430, 2023). "TSC2‐expressing (TSC2+) and ‐deficient (TSC2‐) cells derived from a patient angiomyolipoma were characterised based on expression of known cellular markers." (PMID 37337371, 2023). "In vitro evidence suggested that stimulation of AGTR1 by angiotensin II drives VEGF-A secretion in mTORC1-activated, TSC2-deficient angiomyolipoma cells, leading to increased cell proliferation, which was shown to be blocked by valsartan, an AGTR1 inhibitor." (PMID 36220392, 2022). "Like classic angiomyolipoma, mutations in the TSC2 gene have been reported in pure epithelioid PEComa/epithelioid angiomyolipoma." (PMID 34069976, 2021). "Most rare manifestations were more common in female patients and those with TSC2 mutations, which is in line with findings from previous literature on rare manifestations such as lymphedema and angiomyolipoma." (PMID 34229737, 2021). "As an exception, in tuberous sclerosis complex (mutation in TSC1, 9q34.13 or TSC2, 16p13.3), angiomyolipomas represent the typical lesions and are more frequent in females." (PMID 34572815, 2021). "While this patient was being treated, a case report described a patient with epithelioid angiomyolipoma who had failed everolimus even with a mutation in TSC2 but had an elevated level of PD-L1." (PMID 34301321, 2021). "An analysis of published metabolomics data also revealed that rapamycin treatment significantly decreased glutathione levels in human TSC2-deficient angiomyolipoma cells." (PMID 33646118, 2021). "From a genetic point of view, angiomyolipomas frequently show loss of heterozygosity in TSC2 or TSC1." (PMID 34572815, 2021). "The prevalence of angiomyolipomas was significantly higher in patients with TSC2 vs. TSC1 mutations (57.5 vs. 33%, p < 0.0001)." (PMID 33041968, 2020). "In our study, the prevalence of angiomyolipoma was significantly higher in those with TSC2 mutations." (PMID 33041968, 2020). "Rates of multiple angiomyolipomas, bilateral angiomyolipoma, renal angiomyolipoma lesions of >3 cm were significantly higher in those with TSC2 mutations than those with TSC1 mutations." (PMID 33041968, 2020). "All three of them were female and had TSC2 mutations, with largest angiomyolipoma diameter between 66 and 96 mm." (PMID 33041968, 2020). "We also observed that patients with TSC2 mutations had angiomyolipoma at early age and experienced higher rates of bleeding complications (haematuria and hemorrhage)." (PMID 33041968, 2020). "We have analyzed the expression of EDN1 and of its receptors EDNRA and EDNRB in primary LAM cells as well as in a TSC2 mutated cell line derived from an angiomyolipoma." (PMID 30279475, 2018).
angiomyolipoma (continued). "This unconventional case was also noticed in angiomyolipoma cells and interpreted by TSC2/mTOR signaling deficiency." (PMID 29952716, 2018). "Our results indicate that therapeutic approaches for treatment of patients with angiomyolipoma should focus on the consequences of TSC2/TSC1 loss, including but not limited to mTOR activation." (PMID 27494029, 2016). "LAM patients were older, with a higher rate of pneumothorax, presented more frequently with renal and hepatic angiomyolipomas, and tended to have a TSC2 mutation profile." (PMID 27171001, 2016). "The findings applied to two established in vitro models of TSC2-deficiency: Eker rat uterine leiomyoma cells and human angiomyolipoma 621 cells." (PMID 27458154, 2016). "In these angiomyolipomas, we found consistent involvement of the TSC2 and TSC1 genes that are known to cause TSC, but very few (<5 on average) mutations elsewhere in the protein-coding regions." (PMID 27494029, 2016). "TSC2 mutations were predominant among patients in both trials and were present in nearly all subjects with angiomyolipoma in whom a mutation was identified (97%), whereas TSC1 mutations were rare in those subjects (3%)." (PMID 25782670, 2015). "TSC2-deficient human cells, derived from the angiomyolipoma of a LAM patient, were engineered to co-express both sodium-iodide symporter (NIS) and green fluorescent protein (GFP)." (PMID 22719903, 2012). "Loss of heterozygosity (LOH) of the TSC2 region has been reported, and angiomyolipoma associated with pulmonary lymphangioleiomyomatosis have been shown to contain TSC2 mutations in a small number of cases." (PMID 21949787, 2011). "TSC2 inactivation by mutation is a consistent and likely necessary genetic event in the pathogenesis of most angiomyolipoma." (PMID 21949787, 2011). "TSC-2 gene encodes tuberin, a protein involved in the pathogenesis of kidney tumors, both angiomyolipomas and renal cell carcinomas." (PMID 19265534, 2009). "Using Tsc2-deficient MEFs, human angiomyolipoma-derived 621-101 cells, and xenograft mouse models, it was shown that miR-21 expression was markedly increased in TSC2-deficient cells and was further elevated following rapamycin treatment, despite rapamycin’s role as an mTORC1 inhibitor." (PMID 40558831, 2025). "Additionally, TSC2 patients were more likely to progress to high-risk angiomyolipomas, thus requiring interventions." (PMID 38483608, 2024). "Angiomyolipomas (AMLs) were significantly more prevalent in the TSC2 mutation group (p = 0.018)." (PMID 38832977, 2024). "Of the 13 children with high-risk angiomyolipomas, 8 (62%) had TSC2 mutation, and 1 (7.7%) had TSC1 mutation, while others had NMI or unknown genetics." (PMID 38483608, 2024). "The TSC1 and TSC2 genes behave as classical tumor suppressor genes, with germline loss-of-function mutations accompanied by somatic loss-of-function of the remaining wild-type allele in tumors including angiomyolipomas." (PMID 34680979, 2021). "Patients with TSC2 mutations also had significantly higher rates of multiple angiomyolipomas (92.3 vs. 67.2, p < 0.0001), bilateral angiomyolipomas (87 vs. 47.5%, p < 0.0001) angiomyolipoma lesions >3 cm (31.2 vs. 11.5%, p = 0.0013) and growing angiomyolipomas (23.2 vs. 9.8%, p = 0.0150)." (PMID 33041968, 2020). "Our findings suggest that angiomyolipomas fit this general model of pediatric tumor development, with few somatic mutations and a single critical target of inactivating mutation (in the case of angiomyolipoma, this is usually TSC2 and less commonly TSC1) that initiates and drives tumor development." (PMID 27494029, 2016). "It is unknown whether additional genetic events, beyond loss of TSC1 or TSC2, contribute to angiomyolipoma development, particularly in large tumors requiring surgical resection." (PMID 27494029, 2016). "Thus, UII and the urotensin receptor mediate a pro-oncogenic phenotype in TSC2-deficient human angiomyolipoma cells that requires Erk1." (PMID 27458154, 2016).
angiomyolipoma (continued). "Consistent with extensive previous data and Knudson’s two-hit hypothesis, we identified biallelic inactivation of TSC2 or TSC1 in 30 of 32 angiomyolipomas and LAM tumors including point mutations, small indels, large genomic deletions, and copy neutral LOH." (PMID 27494029, 2016). "Tuberous Sclerosis Complex (TSC) is caused by TSC1 or TSC2 mutations, leading to hyperactivation of mechanistic target of rapamycin complex 1 (mTORC1) and lesions in multiple organs including lung (lymphangioleiomyomatosis) and kidney (angiomyolipoma and renal cell carcinoma)." (PMID 38195686, 2024). "We found that TSC2-null angiomyolipoma-derived (AML-derived) cells produce excessive prostaglandin E2 (PGE2) induced by COX2 and express higher levels of PGE2 receptor 3 (EP3) relative to TSC2-reexpressing cells." (PMID 36927688, 2023). "Renal pathology was further enhanced in TSC2 patients, marked by increased bilateral angiomyolipoma prevalence." (PMID 35440050, 2022). "We next wanted to assess the antitumor activity of Ref-1 inhibitors in an LAM patient angiomyolipoma derived cell line (621-102 AML cells) that lacks functional TSC2." (PMID 36551683, 2022). "Immunohistochemistry studies showed low expression of tuberin (TSC2) in angiomyolipoma, which contains activated mTOR signals, compared to healthy kidneys, authenticating the suppression role of TSC2 on mTOR activity." (PMID 36422197, 2022). "Tumors in TSC, including angiomyolipomas and renal cell carcinomas, develop after somatic “second hit” inactivation of the remaining wild-type allele of TSC1 or TSC2." (PMID 34680979, 2021). "Increasing evidence supports the idea that angiomyolipoma is the prototype of lesions in which the mTOR pathway is hyperactivated due to TSC1/TSC2 gene alterations." (PMID 34069976, 2021). "Just as in the TSC2-/- angiomyolipoma cell line S102, in the primary LAM lung tissue derived cell lines the expression of ADH1, ADH4 and ALDH1A1-2-3 showed the same pattern." (PMID 34178631, 2021). "The other renal features reported at baseline were multiple renal cysts (24.6%), polycystic kidney disease (proven TSC2/PKD1 mutation; 3.4%), renal malignancy (1.4%), and impaired renal function (non-angiomyolipoma-related; 1.9%)." (PMID 33041968, 2020). "Upregulated PARP-1 expression was also found in TSC2-null cells derived from patients with LAM, as well as in TSC2-null xenograft tumors, renal tumors from TSC2 heterozygous mice, human angiomyolipomas, and LAM nodules." (PMID 33072782, 2020). "The angiomyolipoma cell line (CRL4004) has only one inactivated and one normal allele of TSC2, and therefore some of data obtained with this cell line should be interpreted with caution." (PMID 29184052, 2017). "Previous genetic studies have shown that angiomyolipomas arising in TSC patients occur due to biallelic inactivation of either TSC2 or TSC1." (PMID 27494029, 2016). "Analysis of sixteen angiomyolipomas from a TSC subject showed both second hit point mutations and CN-LOH in TSC2, many of which were distinct, indicating that they were of independent clonal origin." (PMID 27494029, 2016). "Angiomyolipoma samples from patients with either sporadic or TSC-associated tumors often display loss of the wild type allele (loss of heterozygosity, LOH) for TSC2, as well as evidence of activation of mTORC1." (PMID 27494029, 2016). "Somatic genetic alterations other than TSC1/TSC2 identified in 23 angiomyolipoma/LAM samples subject to tumor-normal paired exome sequencing." (PMID 27494029, 2016). "More recently, LOH for the TSC2 region was identified in 11 of 12 PEComas, and 6 of 14 ‘classic’ angiomyolipoma." (PMID 21949787, 2011). "Overall, these data indicate that TSC2 inactivation is a consistent and likely necessary genetic event in the pathogenesis of most angiomyolipoma." (PMID 21949787, 2011). "There is one report of a massive liver angiomyolipoma in a 26 year old female with TSC2 disease that regressed after treatment with tamoxifen." (PMID 20146790, 2010).